MEIS1 (Meis homeobox 1)
Diseases named in the same sentence as MEIS1 in open-access papers (continued):
Sharing a sentence is not in itself a finding about the gene and the disease.
tumor (continued). "The interdependence of MEIS1 and HOXB13 to promote tumor suppression implies that changes to either factor enable the other factor to pair with an oncogenic driver." (PMID 32553107, 2020). "Given the correlation between MEIS expression and metastasis within annotated tumor specimens, we investigated the migratory capacity of CWR22Rv1 and LAPC4 cells expressing exogenous MEIS1." (PMID 32553107, 2020). "MEIS1 expression is decreased in ESCC and inversely related to lymph node metastasis and high tumor stage." (PMID 32819319, 2020). "Our studies revealed a tumor suppressive role of Suv39h1 in MLL-r AML that is partially mediated by inactivation of Hoxb13 and Six1, as well as reversion of Hoxa9/Meis1 downstream transcriptomes." (PMID 33037410, 2020). "Our study provides a compelling argument for regulation of proteoglycans by MEIS1 and HOXB13 as a mechanism for MEIS-driven tumor suppression in PrCa." (PMID 32553107, 2020). "We previously demonstrated that depletion of both MEIS1 and MEIS2 in LAPC4 cells was necessary to promote tumor xenograft growth." (PMID 32553107, 2020). "MEIS1 silencing resulted in suppression of the involved genes in cell proliferation (EGF) and EMT (TWIST1), leading to tumor cell differentiation in ESC cell line KYSE‐30." (PMID 31090196, 2019). "We have recently reported a significant correlation between MEIS1/MSI1 over expression and depth of tumor invasion, in which the over expressed cases were observed among the tumors with higher depths of invasion." (PMID 31470870, 2019). "Since tumor cells approximately exhibit markers and properties of embryonic stem cells, low level of OCT4 or SOX2 is necessity for supporting MEIS1 expression to promote the maintenance of differentiation in such cells." (PMID 31090196, 2019). "As expected, tetracycline treatment induced the overexpression of MEIS-1 and reduced tumor growth; and the RFA treatment resulted in tumor size reduction." (PMID 29632641, 2018). "Accordingly, transcript levels for seven of these genes were evaluated, with five of them (MEIS1, HOXA3, OTX2, TWIST1, and PROM1) being underexpressed in the tumor samples." (PMID 25908946, 2015). "In contrast to oncogenic Meis1, its closely related TALE family member, Pbx-regulating protein 1 (Prep1, aka pKnox1), is a tumor suppressor in mice and humans." (PMID 26259236, 2015). "mRNA expression of the candidate genes MEIS1, LDOC1, AGTR1, BAK1, TYMS and DTL were analyzed in 3 cell lines (Hep2, KB and SCC 084), 1 primary HNSCC tumor and 3 normal head and neck tissue samples." (PMID 25186767, 2014). "Prep1 and Meis1 ortholog TALE transcription factors have opposing roles in tumorigenesis: Meis1 serves as an oncogene, Prep1 as a tumor suppressor." (PMID 24809472, 2014). "The same was true for gene expression of a truncated form of MEIS1, MEIS1D27, which misses exon 8 and has a proposed tumor suppression function." (PMID 24244575, 2013). "As an example, clonal analysis of resistant cells strongly implicate MEIS1 as a modifier of ABCB1-mediated resistance, and this is further supported by our analysis of a large panel of tumor cells." (PMID 23442791, 2013). "As a result of the dysregulation, other proteins like MEIS1, MEIS2, TPM1, and ZEB1, which are putative tumor suppressors, are affected." (PMID 24391925, 2013). "By analyzing gene expression patterns and conducting clinicopathological tests on tumor and adjacent tumor-free tissues from 50 ESCC patients, researchers have shown that SALL4 expression positively correlates with that of MEIS1, a homeobox transcription factor." (PMID 38584262, 2024). "Similarly, significantly impaired mRNA and protein levels of MEIS1 were verified in CRC cell lines and tissues and contributed to enhanced cell viability, tumor growth in mice, and oxaliplatin resistance." (PMID 35351858, 2022).
tumor (continued). "MEIS1 could enhance viability of CRC cells and tumor growth in mice and enhance oxaliplatin sensitivity to regress CRC cells by preventing DNA damage repair." (PMID 35351858, 2022). "The inverse association between MEIS1 expression and AR extended further to HOXB13 expression, indicating that in a subset of primary PCa, decreased expression of MEIS1 may be necessary for AR and HOXB13 to drive tumor development and progression." (PMID 32681068, 2020). "Therefore, in addition to the prognostic utility of MEIS1/2 expression in PrCa, we report a mechanism of MEIS-driven tumor suppression that has potential to be exploited clinically." (PMID 32553107, 2020). "Thus, both MEIS1 and full-length MEIS2 are sufficient to slow PrCa cell proliferation and tumor growth via reduced G1/S phase transition and decreased migratory capacity." (PMID 32553107, 2020). "Four recurrent deleterious variants corresponding to the CHD1L (99.0%), GFM1 (91.7%), MEIS1 (90.6%) and NFX1 (93.8%) genes were found in the majority of the tumor samples in the study cohort, but in none of the normal controls." (PMID 30416686, 2018). "To investigate the role of the Meis1 gene in skin carcinogenesis, we subjected 32 K14CreER-Meis1fl/fl mice and 43 Meis1fl/fl control mice to the DMBA/TPA chemical carcinogenesis protocol and monitored their tumor development for a period of 35 weeks." (PMID 25013928, 2014). "Decrease in MEIS1, GFI1 and cMYC, has been shown to inhibit tumour cell growth, and an increase in TRIB2 may be pro-apoptotic." (PMID 24708856, 2014). "In comparison, only one out of four tumors without MEIS1 methylation had lower MEIS1 expression in the tumor relative to the paired normal tissue." (PMID 24244575, 2013). "In PC, there is no tumor aggression in patients with high Meis1 and Meis2 expression." (PMID 33402862, 2020). "This indicates that the competition of Meis1 and Prep1 for AP-1 binding sites may be involved in the tumor versus non-tumor decision." (PMID 26259236, 2015). "However, Meis1 and Prep1 differ from c-Myc which at high levels of expression in tumor cells does not enlarge its set of target genes, but rather occupies more enhancers activating their transcription." (PMID 26259236, 2015). "Since Prep1 exerts a tumor suppressive function, we tested whether the absence of Prep1 would allow Meis1 to induce AML in vivo without HoxA9 overexpression." (PMID 24809472, 2014). "According to the role of TWIST1 in EMT, its significant decreased expression following MEIS1 silencing in KYSE‐30 cells may inhibit EMT progress and invasiveness behavior of the cells, and reverse the process of mesenchymal transition which may result in tumor cell differentiation." (PMID 31090196, 2019). "Therefore, therapeutics targeting the role of MEIS1 in oxaliplatin resistance are developed and our results suggest that the combination of oxaliplatin with either ELFN1-AS1 ASO or EZH2 inhibitor GSK126 could largely suppress tumor growth and reverse oxaliplatin resistance." (PMID 35351858, 2022). "Furthermore, a correlation of MEIS1 and SALL4 was found in tumor samples without metastasis, compared to metastasized ESCCs." (PMID 32819319, 2020). "Here we elucidated the correlation between MEIS1 and stemness marker SALL4 in ESCC and revealed significant correlation between the genes in different early pathological features of the disease including non-invaded state, at primary stages of tumor progression." (PMID 32819319, 2020).
infection (4 papers, 2016 to 2022). The state of being infected such as from the introduction of a foreign agent such as serum, vaccine, antigenic substance or organism. "We first selected a HCC cell line MHCC97-H which has very low endogenous MEIS-1 expression, MEIS-1 was overexpressed via infection of its adenovirus-vectors in MHCC97-H cells." (PMID 29632641, 2018). "The protein level of MEIS1 was significantly increased upon Ad-MEIS1 infection." (PMID 28270206, 2017).
hematologic malignancies (3 papers, 2016 to 2024). "Homeobox genes and the cofactor MEIS1 have been directly implicated in hematological malignancies." (PMID 27579617, 2016).
cardiovascular diseases (2 papers, 2017 to 2022). "RLS patients should be considered differently depending on MEIS1 genotype, some being potentially at risk for cardiovascular disorders." (PMID 28425489, 2017).
adenocarcinoma (1 paper, 2009). A common cancer characterized by the presence of malignant glandular cells. "Another finding of our study was the remarkable regulation of hox genes in adenocarcinoma, for example Hoxa5, Hoxb5, Meis1 and Meis2." (PMID 19812696, 2009). "Furthermore some of the homeobox genes, e.g. Hoxa5, Hoxb5, Meis1 and Mrg1 were up to 9-fold repressed in adenocarcinomas." (PMID 19812696, 2009).
kidney disease (1 paper, 2024). "To validate the potential role of Meis1 in kidney disease, we performed immunohistochemical and immunofluorescence staining." (PMID 39162106, 2024).
prostate (1 paper, 2020). "A recent study did not detect an effect of the G84E mutation on interaction with MEIS1, suggesting alternative mechanisms for HOXB13 mutations in driving prostate carcinogenesis beyond disruption of MEIS interaction." (PMID 32553107, 2020).
Respiratory diseases (1 paper, 2015). "Another example, topological module 11, with 4 genes, contains MEIS1, MEIS2 and PBX1, which are disease genes associated with Cardiovascular, Neurological, Psychiatric, Endocrine and Respiratory diseases, and these were also defined as a disease module." (PMID 26399914, 2015).
MEIS1 also shares sentences with these, for which no sentence is quoted: mental disorder (4 papers); schizophrenia (3); atrial fibrillation (2); cervical carcinoma (2); colon adenocarcinoma (2); depression (2); head and neck squamous cell carcinoma (2); hematopoietic cancer (2); lymphoid neoplasm (2); lymphoma (2); malignant peripheral nerve sheath tumor (2); pancreatic adenocarcinoma (2); uterine carcinosarcoma (2); adrenocortical carcinoma (1); angina (1); Aphasia (1); B-cell neoplasm (1); B-cell precursor acute lymphoblastic leukemia (1); benign tumors (1); bladder urothelial carcinoma (1); blood cancers (1); breast invasive carcinoma (1); Brugada syndrome (1); Brunner syndrome (1); cardiac hypertrophy (1); chronic kidney disease (1); CNS lymphomas (1); colon adenoma (1); congenital heart disease (1); COVID-19 (1).
A further 34 diseases each share a sentence with MEIS1 in 1 paper.